ARHGEF37 (Rho guanine nucleotide exchange factor 37)
Description:
Probable guanine nucleotide exchange factor (GEF) involved in clathrin-mediated endocytosis, probably playing a role in the late stages of the process.
Synonyms: FLJ41603
Tractability: No criterion of Open Targets' tractability assessment is met for any kind of drug.
Gene: Protein-coding gene on chromosome 5 (149,551,947 to 149,634,968, forward strand). Ensembl gene ENSG00000183111.
Subcellular location (Human Protein Atlas): Cytosol
Pathways (Reactome):
Signal Transduction: G alpha (12/13) signalling events; NRAGE signals death through JNK
Gene Ontology:
Molecular function: guanyl-nucleotide exchange factor activity
Biological process: clathrin-dependent endocytosis
Cellular component: cytoplasm
Genetic constraint (gnomAD): Loss-of-function variants: 54 observed, 70.39 expected, observed/expected ratio (o/e) 0.77, 90% interval 0.62 to 0.96. The upper end of that interval is the gene's LOEUF score, 0.96, which puts it in group 4 of 6, group 1 being the genes least tolerant of losing a copy. Missense variants: 751 observed, 849.03 expected, observed/expected ratio (o/e) 0.88, 90% interval 0.83 to 0.94. Synonymous variants: 324 observed, 360.51 expected, observed/expected ratio (o/e) 0.9, 90% interval 0.82 to 0.99.
Homologues: Orthologues: chimpanzee ARHGEF37 (99% identical), macaque ARHGEF37 (96% identical), dog ARHGEF37 (85% identical), guinea pig ARHGEF37 (82% identical), rabbit ARHGEF37 (81% identical), rat Arhgef37 (81% identical), pig ARHGEF37 (80% identical), mouse Arhgef37 (80% identical), tropical clawed frog arhgef37 (40% identical), zebrafish arhgef37 (38% identical), Caenorhabditis elegans dnbp-1 (21% identical). Paralogues in human: DNMBP (31% identical), ARHGEF38 (29% identical).
Diseases named in the same sentence as ARHGEF37 in open-access papers:
ARHGEF37 is named in the same sentence as 7 diseases in open-access papers, as found by Europe PMC text mining. Sharing a sentence is not in itself a finding about the gene and the disease. The quoted sentences say what the papers report.
hepatocellular carcinoma (5 papers, 2022 to 2025). A malignant tumor that arises from hepatocytes. "For example, in hepatocellular carcinoma cells, ARHGEF37 can activate CDC42 by interacting with it." (PMID 36870986, 2023).
muscular disease (1 paper, 2025). Myopathy is a peripheral nervous system disease consisting of any abnormal condition or disease of the muscular tissues; commonly designates a disorder involving skeletal muscle. "In terms of disease association, ARHGEF37 is linked with various disease states, including muscular diseases, neurodegenerative disorders, and certain infectious diseases." (PMID 40313599, 2025).
tumor (4 papers, 2022 to 2025). "To address the mechanism underlying pulmonary metastasis, we found that ARHGEF37-mediated Cdc42 activation plays a vital role in lung metastasis via modulation of the adhesion and extravasation of tumor cells." (PMID 35869555, 2022). "In the present study, we demonstrated that ARHGEF37-mediated Cdc42 activation promoted tumor cell adhesion and further extravasation across the monolayer of the endothelium by enhancing the formation of invadopodia." (PMID 35869555, 2022). "In the current study, we found that Rho guanine nucleotide exchange factor 37 (ARHGEF37) was upregulated in human HCC samples and was associated with tumor invasiveness, pulmonary metastasis and poor prognosis." (PMID 35869555, 2022). "Given that ARHGEF37 is associated with EC adherence and trans-endothelial migration via regulating Cdc42 activity, we speculated that a Cdc42 inhibitor would be potential therapeutic agent for ARHGEF37-mediated tumor cell invasion." (PMID 35869555, 2022). "To confirm our hypothesis, we performed both in vitro and in vivo assays, the results of which demonstrated that overexpression of ARHGEF37 led to an increased adhesion and trans-endothelial migration capability of tumor cells and invadopodia formation." (PMID 35869555, 2022). "Furthermore, ZCL278 treatment interfered with ARHGEF37-transduced tumor cell adhesion to an EC monolayer compared that of with the vehicle group." (PMID 35869555, 2022). "To examine whether dysregulation of ARHGEF37 has affected on these intercellular junctions, we observed the pericyte–EC interaction in a 2D co-culture system with tumor cells." (PMID 35869555, 2022). "Overexpressing ARHGEF37 significantly enhanced the extravasation and metastatic capability of HCC cells via facilitating tumor cell adhesion to endothelial cells and trans-endothelial migration." (PMID 35869555, 2022).
cancer (2 papers, 2022 to 2025). A tumor composed of atypical neoplastic, often pleomorphic cells that invade other tissues. "In line with above hypothesis, ARHGEF37 overexpression significantly facilitated the adhesion of cancer cells to HMVEC-L cells, whereas silencing ARHGEF37 impaired their adherence." (PMID 35869555, 2022). "Taken together, these results demonstrate that ARHGEF37 facilitates the adhesion to endothelial monolayers and the trans-endothelial migration of HCC cancer cells both in vivo and in vitro." (PMID 35869555, 2022).
ARHGEF37 also shares sentences with these, for which no sentence is quoted: colon cancer (2 papers); fibromyalgia (1); infectious disease (1).